HSP90B3P (heat shock protein 90 beta family member 3, pseudogene)
Synonyms: GRP94c; TRA1P2; TRAP2
Gene: Processed pseudogene on chromosome 1 (91,642,516 to 91,644,082, forward strand). Ensembl gene ENSG00000203914.
Diseases named in the same sentence as HSP90B3P in open-access papers:
HSP90B3P is named in the same sentence as 2 diseases in open-access papers, as found by Europe PMC text mining. Sharing a sentence is not in itself a finding about the gene and the disease. The quoted sentences say what the papers report.
pemphigoid (1 paper, 2021). "Thus, the discovery of significant upregulation of Hsp90 genes HSP90B1, HSP90B2P, HSP90B3P in laminin-332 pemphigoid IgG treated may present a possible therapeutic approach." (PMID 34899732, 2021).
cancer (1 paper, 2017). A tumor composed of atypical neoplastic, often pleomorphic cells that invade other tissues. "Seven (PA2G4P4, ATP5EP2, FTH1P3, ANXA2P3, ANXA2P1, HNRNPA1P33, and HSP90B3P) of the 14 pseudogenes that our analysis revealed as important for pan-cancer classification were previously found to be differentially expressed in various cancers." (PMID 28673244, 2017).